ENSG00000207094
Synonyms: LOC124900238
Gene: Small nucleolar RNA gene on chromosome 7 (88,449,092 to 88,449,231, reverse strand). Ensembl gene ENSG00000207094.
Gene Ontology:
Biological process: RNA processing
Cellular component: nucleolus
Homologues: Paralogues in human: SNORA67 (91% identical).